IGF2R (insulin like growth factor 2 receptor)
Diseases named in the same sentence as IGF2R in open-access papers (continued):
Sharing a sentence is not in itself a finding about the gene and the disease.
glioma (5 papers, 2016 to 2024). A benign or malignant brain and spinal cord tumor that arises from glial cells (astrocytes, oligodendrocytes, ependymal cells). "Insulin-like growth factor-binding protein 2, a glioma marker linked to poor prognosis, binds to and modulates IGF2R." (PMID 27770278, 2017). "Insulin-like growth factor 2-receptor (IGF2R) was measured at higher levels in more invasive GBM EVs and tumour mRNA levels were higher in gliomas than normal brain." (PMID 27770278, 2017). "We have found that IGF2R, INSR, and IGF1R have a tight relationship with SOX10 in gliomas." (PMID 36524115, 2022).
intrauterine growth restriction (5 papers, 2011 to 2022). "In addition, decreased protein expression of IGF2R in the rat intrauterine growth restriction has been associated with decreased glomerular number, and IGFR has been associated with promoting nephrogenesis and kidney organogenesis." (PMID 31690042, 2019). "Both are involved in regulating conceptus growth and development, with deletion of IGF2R leading to placental and fetal overgrowth, whereas deletion of IGF2 leads to placental and fetal growth restriction, in mice." (PMID 36176700, 2022). "Interestingly, intrauterine growth restriction (IUGR) in rats is accompanied by a decreased glomerular number and reduced IGF2R protein expression." (PMID 21637383, 2011).
lung carcinoma (5 papers, 2018 to 2024). "Interestingly, the IGF axis is a complex molecular network (including peptide‐ligands IGF1, IGF2, and insulin, and the receptors IGF1R, IGF2R, and INSR) that is involved in a wide variety of neoplasms such as prostate, breast, colorectal, and lung cancers." (PMID 34668636, 2022).
metabolic syndrome (5 papers, 2020 to 2022). A cluster of metabolic risk factors for CARDIOVASCULAR DISEASES and TYPE 2 DIABETES MELLITUS. "As such, MiR-143-3p knockdown was shown to protect against insulin resistance in patients with metabolic syndrome via targeting of IGF2R and activation of the insulin signaling pathway." (PMID 33207733, 2020). "Moreover, compared to controls, significantly elevated MiR-143-3p levels in serum and urine have been found in patients with metabolic syndrome, with the insulin-like growth factor 2 receptor (IGF2R) gene being among the target genes of MiR-143-3p." (PMID 33207733, 2020).
prostate carcinoma (5 papers, 2013 to 2025). A carcinoma that arises from epithelial cells of the prostate gland. "Here, we identify neoantigens encoded by Ptprs and Igf2r that are shared across murine mismatch repair-deficient colorectal and breast tumors and unexpectedly conserved in human colorectal, endometrial, gastric, and prostate cancers." (PMID 41256707, 2025). "Using prostate cancer as a case study, the best features were identified and utilized to train machine learning algorithms to predict 5 novel promising therapeutic targets for prostate cancer: IGF2R, C5AR, RAB7, SETD2 and NPBWR1." (PMID 38983753, 2024). "IGF2R is directly involved in the insulin-like growth factor axis, a pathway known to be important in prostate cancer and already proposed as a potential therapeutic avenue for prostate cancer." (PMID 38983753, 2024). "M6P/IGF2R Dom11mut was found to be lessgrowth-inhibitory than the wt receptor under standard culture conditions, in line with studiesperformed on LNCaP and PC-3 human prostate cancer cells.However, this M6P/IGF2R mutant is still capable of restricting anchorage-independent growth ofSCC-VII cells." (PMID 23347038, 2013). "Additionally, four novel targets were predicted (IGF2R, C5AR/C5AR1, RAB7, and SETD2) which are all involved in molecular pathways closely connected to prostate cancer, with some having been recently proposed as suitable targets for other types of cancers." (PMID 38983753, 2024).
adenoma (4 papers, 2019 to 2024). A neoplasm arising from the epithelium. "Again, histological confirmation with anti-IGF2R antibodies, suggested that there was mosaic loss of Igf2r following conditional disruption in adenoma." (PMID 31388182, 2019). "The comparative analysis of the transcriptional profiles of NAGs and ACAs revealed the overexpression of specific genes in all adenomas compared to normal adrenals, including IGF2R, GAS2 and SLBP." (PMID 39167619, 2024). "Paradoxically, when ApcMin/+, H19Δm/+p, Igf2r+m/R2Δ were then combined, significant adenoma progression was observed, with a marked increase in both adenoma number and variation compared to wild-type littermates especially in the distal small intestine (p = 0.0183)." (PMID 31388182, 2019). "In ApcMin/+, H19Δm/+p, there appeared no significant increase in adenoma number, whereas in ApcMin/+, Igf2r+m/R2Δ there was a significant reduction in the middle part of the small intestine (p = 0.0187), compatible with Igf2r having adenoma suppressor function." (PMID 31388182, 2019). "The xenografted mice were treated with IGF2R/CI-M6PR, an inhibitor of IGF2, and showed a decrease in Igf2-dependent adenoma phenotype." (PMID 38542291, 2024). "The introduction of Igf2rI1565A/+p did not alter the distribution of IGF2R protein within adenoma as expected." (PMID 31388182, 2019).
bladder cancer (4 papers, 2017 to 2021). "Similar to our findings, low expression of IGF2R in non-small cell liver cancer has been associated with poor prognosis and high expression in bladder cancer has been associated with good prognosis." (PMID 33237942, 2020). "Previous survival analysis of TCGA-BLCA samples was shown in the figure, indicating that high IGF2R expression level predicted poor bladder cancer OS." (PMID 34365465, 2021). "In conclusion, our study showed that hsa_circ_0007813 was upregulated in bladder cancer, and it can efficiently sponge hsa-miR-361-3p to regulate IGF2R expression." (PMID 34365465, 2021). "Using qRT-PCR, we next figured out that relative hsa_circ_0007813 expression level was negatively correlated with hsa-miR-361-3p level, and positively correlated with IGF2R level, in bladder cancer tissues." (PMID 34365465, 2021).
cardiac hypertrophy (4 papers, 2016 to 2023). "Enhanced IGF2R expression will cause cardiac hypertrophy and cardiomyocytes apoptosis." (PMID 27167200, 2016). "Our results suggest that though ETS exposure might cause cardiac autophagy amongst youngsters, the loss of the longevity Sirt-1 protein and the increase in IGF2R cardiac hypertrophy signaling could still promote heart diseases that are age-specific." (PMID 27167200, 2016). "In conclusion, our current findings show that ETS exposure can reduce the Sirt-1 level in hearts, enhance the activation of the cardiac hypertrophy-related IGF2R signaling pathway and enhance cardiac autophagy." (PMID 27167200, 2016). "Furthermore, the IGF2R cardiac hypertrophy signaling pathway was also triggered, although cardiac apoptosis and hypertrophy were not induced." (PMID 27167200, 2016). "A recent study has shown that PM2.5 exposure can induce cardiac hypertrophy via circRNA_0001859, which suppressed miR-29b-3p, resulting in an enhanced Ctnnb1 level and activated the downstream pathway molecules like LEF1/IGF-2R." (PMID 37626874, 2023).
hemangioma (4 papers, 2019 to 2023). A benign vascular lesion characterized by the formation of capillary-sized or cavernous vascular channels. "Meanwhile, another study reported a loss of IGF2R-induced apoptosis in hemangioma cells." (PMID 31748500, 2019). "However, there is also some data indicating IGF2R involvement in hemangioma proliferation." (PMID 33673334, 2021).
lysosomal storage disease (4 papers, 2020 to 2025). A metabolic disorder caused by mutations in proteins critical for lysosomal function, including lysosomal enzymes, lysosomal integral membrane proteins, and proteins involved in the post-translational modification and trafficking of lysosomal proteins. "The phenomenon of decreased uptake through IGF2R/M6P endocytosis has been documented for several lysosomal storage disorders, such as in fibroblasts from Pompe and Niemann Pick patients." (PMID 32486191, 2020). "The calcium-independent mannose-6-phosphate (M6P) receptor IGF2R is responsible for the vesicular transport of over 70 hydrolases with M6P domains from TGN and plasma membrane to the lysosome, enabling enzyme replacement therapies for BD and other lysosomal storage diseases." (PMID 41173878, 2025).
squamous cell carcinoma (4 papers, 2012 to 2022). A carcinoma arising from squamous epithelial cells. "We have earlier observed a similar proteinase inhibition profile for the invasive properties of M6P/IGF2R-deficient murine squamous cell carcinoma cells." (PMID 22521359, 2012). "In squamous cell carcinoma cells, the anti-invasive activity of M6P/IGF2R appears to rely on restriction of the pericellular accumulation of M6P-tagged lysosomal proteinases." (PMID 22521359, 2012). "IGF2R was expressed in the cytoplasm or nuclei of squamous cell carcinoma cells but not in the normal squamous epithelium." (PMID 36299463, 2022).
viral infection (4 papers, 2019 to 2025). "The 7-Mb QTL region on SSC1 and the 40-Mb QTL region on SSC10 only overlapped with enriched DE genes for bacterial or viral infection but harbors 2 immune related genes, IGF2R and TAGAP." (PMID 35100362, 2022). "Depending on the ligand to which it binds, IGF2R is involved in modulating a number of biological pathways including cell migration, wound healing, angiogenesis, apoptosis and the response to viral infection." (PMID 31748618, 2019). "In addition to the EGFR transcript, IGF2R is also a low-expressed gene during the propagation phase of the viral infection." (PMID 38813031, 2023). "Additionally, some studies have suggested that IGF2R may play a role in the immune response to viral infections, although further research is necessary to fully understand this role." (PMID 38813031, 2023).
Alzheimer disease (3 papers, 2011 to 2021). A progressive, neurodegenerative disease characterized by loss of function and death of nerve cells in several areas of the brain leading to loss of cognitive function such as memory and language. "CIM6P/IGF2R has been implicated in several aspects of Alzheimer’s disease (AD): levels of CIM6P/IGF2R decrease with the presence of APOE4 alleles, and overexpression of CIM6P/IGF2R increases amyloid precursor protein processing and amyloid-beta (Aβ) production, a hallmark alteration in AD." (PMID 32369018, 2020).
autism (3 papers, 2011 to 2024). Persistent deficits in social interaction and communication and interaction as well as a markedly restricted repertoire of activity and interest as well as repetitive patterns of behavior. "In-depth analysis revealed that IGF1R and IGF2R regulate a group of 182 genes within IN-PV neurons, including 18 genes known to be associated with autism." (PMID 39376742, 2024). "Differentially expressed autism susceptibility genes after knock out IGF1R and IGF2R in IN-PV cells." (PMID 39376742, 2024). "This suggests that disruptions in the structure and function of IGF1R and IGF2R could lead to developmental and functional impairments in IN-PV neurons, potentially contributing to the pathophysiology of autism." (PMID 39376742, 2024).
COVID-19 (3 papers, 2022 to 2023). A disease caused by infection with severe acute respiratory syndrome coronavirus 2. "Overall, although the EGFR and IGF2R genes have been implicated in COVID-19, further research is required to fully comprehend their significance in the disease and to identify potential targets for treatments." (PMID 38813031, 2023). "Specifically, we have emphasized the significance of the ANPEP and IGF2R genes, which play unique roles in the progression of COVID-19 from the initiating phase to the propagating phase." (PMID 38813031, 2023). "It is important to note that while the roles of EGFR and IGF2R in the context of COVID-19 have been investigated, their precise significance in the disease is still being explored." (PMID 38813031, 2023). "In conclusion, the expression of critical biogenomic markers, including the ACE2, ANPEP, EGFR, and IGF2R genes, plays a significant role in the development of mild clinical presentations in pediatric COVID-19 cases." (PMID 38813031, 2023). "The study results indicated that the expression of critical biogenomic markers, such as the first-phase (ACE2 and ANPEP) and second-phase (EGFR and IGF2R) receptor genes, was crucial in the genesis of mild clinical presentations of pediatric COVID-19." (PMID 38813031, 2023). "The present study has revealed that the expression of the IGF2R gene is higher in pediatric patients with COVID-19." (PMID 38813031, 2023). "In light of these data, the high expression of the IGF2R gene in pediatric patients may have a protective role and could contribute to the milder clinical course of COVID-19 observed in this population." (PMID 38813031, 2023). "Particularly in adult patients, screening for ANPEP and IGF2R gene expressions could be valuable for predicting the severity of the clinical course of COVID-19." (PMID 38813031, 2023). "The interrelationship between EGFR and IGF2R might also play a role in impeding the progression of COVID-19 from the propagating phase to the complicating phase in pediatric patients." (PMID 38813031, 2023). "The interrelationship between the EGFR and IGF2R genes might impede the progression of COVID-19 from the propagating phase to the complicating phase in pediatric patients." (PMID 38813031, 2023). "In lung cells infected with SARS-CoV-2, IGF2R has been found to be downregulated, and this downregulation may contribute to the development of lung inflammation and damage observed in severe cases of COVID-19." (PMID 38813031, 2023). "One possible explanation for the divergent clinical courses observed between adult and pediatric COVID-19 patients is alterations in the ANPEP and IGF2R genes." (PMID 38813031, 2023). "There was a positive correlation between the COVID-19-related protein RPL9 and IGF2R." (PMID 35720320, 2022). "There was a positive correlation between the COVID-19-related protein RPS3 and IGF2R." (PMID 35720320, 2022). "Previous research demonstrated that with increasing exposure time to SARS-CoV-2, two receptors, EGFR and IGF2R, which play crucial roles in the RAS signaling pathway, are significantly downregulated in infected human bronchial epithelial cells during the propagating phase of COVID-19." (PMID 38813031, 2023). "Furthermore, adult COVID-19 patients with hypertension may more frequently and easily progress from the propagation phase to the complication phase due to alterations in the EGFR and IGF2R genes." (PMID 38813031, 2023). "The results of the current study support the hypothesis that the mild clinical presentations of pediatric COVID-19 are driven by the expression of critical biogenomic markers, specifically the first-phase receptor genes (ACE2 and ANPEP) and second-phase receptor genes (EGFR and IGF2R)." (PMID 38813031, 2023).
heart failure (3 papers, 2015 to 2023). Inability of the heart to pump blood at an adequate rate to meet tissue metabolic requirements. "CREB potentially plays a crucial role in providing protection from hypoxia-induced IGF2R signaling and apoptosis in H9c2 cardiomyoblast cells, thereby it inhibits heart failure." (PMID 26610485, 2015). "We proposed that hypoxic conditions would stimulate IGF2R activation, thereby triggering downstream signaling cascades, promoting cardiomyocyte apoptosis and, finally, resulting in heart failure." (PMID 26610485, 2015). "In cardiomyoblast cells, IGF2R plays a critical role in the regulation of cell apoptosis, which might contribute to heart failure." (PMID 26610485, 2015).
laryngeal carcinoma (3 papers, 2013 to 2024). Carcinoma that arises from the laryngeal epithelium. "According to our knowledge, we were the first to discover that the IGF2R protein is abnormally expressed in laryngeal cancer tissue." (PMID 36299463, 2022). "Secondly, IGF2R was not studied in vitro; hence, there is presently no in-depth comprehension of IGF2R’s role in laryngeal cancer invasion and metastasis." (PMID 36299463, 2022).
neuroblastoma (3 papers, 2018 to 2024). Neuroblastoma (NB) is the most common solid, extracranial childhood tumor. "Inhibition of expression of either IGF2R or GNPTAB impaired invasiveness of neuroblastoma cell lines SK-N-SH and SK-N-AS." (PMID 38750105, 2024). "We found that a construct containing residues 1–709 of SPG15 brought down CIMPR (IGF2R) as one of its top hits from SH-SY5Y neuroblastoma cells." (PMID 29381698, 2018).
ovarian carcinoma (3 papers, 2012 to 2019). A malignant neoplasm originating from the surface ovarian epithelium. "Moreover, LOH at M6P/IGF2R is well known to be a frequent event in primary ovarian cancers and a low D6S1581 copy number was associated with platinum-resistant condition in ovarian cancer." (PMID 22849543, 2012). "The results of qPCR microarray analysis showed that several genes involved in MAPK pathways, including c-Fos, Egfr, and Igf2r, had higher expression levels in OCICs than in primary ovarian cancer cells." (PMID 25369529, 2014). "Genomic region proximal to M6P/IGF2R, a promising target, and its role in ovarian cancer is currently under investigation." (PMID 22849543, 2012).
Type 2 Diabetes (3 papers, 2015 to 2021). "IGF2R (insulin-like growth factor two receptor) interacts with insulin receptors for energy homeostasis, and the dysregulation of the gene is associated with type 2 diabetes." (PMID 34002691, 2021). "Soluble IGF2R could directly affect susceptibility to type 2 diabetes, or indirectly through growth hormone (GH) and IGF1." (PMID 25922844, 2015). "With regard to glucose homeostasis, genetic variants in the IGF2R gene have been shown to be associated with both type 1 and type 2 diabetes (T2DM)." (PMID 25922844, 2015). "The aim of this study is to investigate the insulin-like growth factor type 2 (IGF2R) gene and circulating soluble IGF2R in relation to type 2 diabetes (T2DM)." (PMID 25922844, 2015).
atherosclerosis (2 papers, 2018 to 2021). A disease characterized by the build-up of fatty material and calcium deposition in the arterial wall resulting in partial or complete occlusion of the arterial lumen. "Overexpression of miR-210-3p by inhibiting the IGF-2/IGF-2R axis could inhibit the expression of CD36 and NF-κB, then led to a reduction in the inflammatory response of macrophages and lipid accumulation in atherosclerosis." (PMID 33768092, 2021).
Cirrhosis (2 papers, 2003 to 2009). A chronic disorder of the liver in which liver tissue becomes scarred and is partially replaced by regenerative nodules and fibrotic tissue resulting in loss of liver function. "In addition to the focal upregulation of IGF-2, we observed reduced M6P/IGF-2R-specific immunostaining in cirrhosis when compared to normal liver." (PMID 12618883, 2003). "All of the 10 specimens with cirrhosis related to HBV or HCV infection were among those cases with clusters of hepatocytes overexpressing IGF-2, and altered M6P/IGF-2R staining patterns were common to all cirrhotic specimens." (PMID 12618883, 2003). "This has prompted us to use in situ hybridisation and immunohistology to assess cellular levels of IGF-2 transcripts and M6P/IGF-2R antibody staining patterns in cases of cirrhosis of different aetiologies without morphological evidence of premalignant or malignant changes." (PMID 12618883, 2003). "In addition, an abrogation of IGF2R could represent a selective advantage at the cirrhosis stage by impairing antiproliferative and pro-apoptotic signals induced by TGF-β, which is overexpressed in cirrhosis." (PMID 21994573, 2009).